RASGRF2 (Ras protein specific guanine nucleotide releasing factor 2)
Description:
Functions as a calcium-regulated nucleotide exchange factor activating both Ras and RAC1 through the exchange of bound GDP for GTP. Preferentially activates HRAS in vivo compared to RRAS based on their different types of prenylation. Functions in synaptic plasticity by contributing to the induction of long term potentiation.
Synonyms: Ras-GRF2; GRF2
Tractability: Antibody: its Gene Ontology location is reachable by antibodies, with high confidence; UniProt places it where antibodies can reach, with medium confidence. PROTAC: UniProt records ubiquitination sites on it; its protein half-life has been measured.
Gene: Protein-coding gene on chromosome 5 (80,960,310 to 81,230,162, forward strand). Ensembl gene ENSG00000113319.
Subcellular location: Cytoplasm; Cell membrane; Endoplasmic reticulum membrane
Subcellular location (Human Protein Atlas): Endoplasmic reticulum
Pathways (Reactome):
Signal Transduction: CDC42 GTPase cycle; G alpha (12/13) signalling events; NRAGE signals death through JNK; RAC1 GTPase cycle; RAF/MAP kinase cascade; RHOA GTPase cycle
Neuronal System: Ras activation upon Ca2+ influx through NMDA receptor
Gene Ontology:
Molecular function: guanyl-nucleotide exchange factor activity
Biological process: response to endoplasmic reticulum stress; Ras protein signal transduction; regulation of small GTPase mediated signal transduction; postsynaptic modulation of chemical synaptic transmission; small GTPase-mediated signal transduction
Cellular component: endoplasmic reticulum; cytosol; plasma membrane; cytoplasm; endoplasmic reticulum membrane; glutamatergic synapse; postsynapse
Genetic constraint (gnomAD): Loss-of-function variants: 70 observed, 139 expected, observed/expected ratio (o/e) 0.5, 90% interval 0.41 to 0.61. The upper end of that interval is the gene's LOEUF score, 0.61, which puts it in group 2 of 6, group 1 being the genes least tolerant of losing a copy. Missense variants: 1,086 observed, 1,527.3 expected, observed/expected ratio (o/e) 0.71, 90% interval 0.68 to 0.75. Synonymous variants: 486 observed, 551.34 expected, observed/expected ratio (o/e) 0.88, 90% interval 0.82 to 0.95.
Homologues: Orthologues: chimpanzee RASGRF2 (99% identical), macaque RASGRF2 (99% identical), pig RASGRF2 (97% identical), dog RASGRF2 (97% identical), rat Rasgrf2 (92% identical), mouse Rasgrf2 (92% identical), guinea pig RASGRF2 (89% identical), zebrafish rasgrf2b (86% identical), tropical clawed frog rasgrf2 (86% identical), rabbit RASGRF2 (85% identical), zebrafish rasgrf2a (81% identical). Paralogues in human: RASGRF1 (68% identical), RAPGEF6 (16% identical), RAPGEF2 (16% identical), SOS2 (15% identical), SOS1 (15% identical), RAPGEF1 (13% identical), RAPGEF4 (11% identical), RAPGEF3 (10% identical), RALGDS (10% identical), RAPGEF5 (10% identical), RGL3 (9% identical), RASGRP4 (9% identical), and 12 more.
Diseases named in the same sentence as RASGRF2 in open-access papers:
RASGRF2 is named in the same sentence as 47 diseases in open-access papers, as found by Europe PMC text mining. Sharing a sentence is not in itself a finding about the gene and the disease. The quoted sentences say what the papers report.
breast carcinoma (4 papers, 2019 to 2025). "We previously reported that high AnxA6 and low RasGRF2 expression is associated with poorer distant relapse-free survival of basal-like breast cancer patients compared to patients with low AnxA6 and high GRF2 expressing basal-like breast cancer." (PMID 32298357, 2020). "Methylation of PAX6, GSTP1, RASGRF2, and AKR1B1 promoters has been previously reported to be associated with lymph node metastasis of breast cancer." (PMID 36454866, 2022). "On the contrary, up-regulation of AnxA6 in the basal-like HCC1806 cells and MDA-MB-468 cells resulted in a decrease in RasGRF2 expression and this was also confirmed in 11 basal-like breast cancer cell lines at the mRNA level." (PMID 30719209, 2019). "Studies have found that the promoters of the AKR1B1 and RASGRF2 genes were highly methylated in breast cancer, which may serve as candidate methylation biomarkers for early breast cancer detection." (PMID 36454866, 2022). "But TCGA data showed that RASGRF2, AKR1B1 and CRMP1 were low expressed in breast Cancer tissues, while RHOF was high expressed in breast Cancer tissues." (PMID 36454866, 2022). "AKR1B1, RASGRF2, CRMP1, BNIP3, GSTP1, HOXA5 and PAX6 genes were methylated in ER-positive and HER2-negative breast cancer with ALNM." (PMID 36454866, 2022). "In addition, Cancer Genome Atlas (TCGA) data showed that RASGRF2, AKR1B1 and CRMP1 were low expressed in breast Cancer tissues, while RHOF was high expressed in breast Cancer tissues." (PMID 36454866, 2022). "Furthermore, in addition to highly methylated AKR1B1, RASGRF2 and CRMP1 gene promoters, BNIP3, GSTP1, HOXA5 and PAX6 gene promoters were also methylated in ER-positive and HER2-negative breast cancer with ALNM." (PMID 36454866, 2022). "Moreover, in addition to highly methylated AKR1B1, RASGRF2 and CRMP1 gene promoters, BNIP3, GSTP1, HOXA5 and PAX6 gene promoters were also methylated in ER-positive and HER2-negative breast cancer with ALNM." (PMID 36454866, 2022). "Additionally, aberrant methylation patterns in the AKR1B1, RASGRF2, CRMP1, BNIP3, GSTP1, HOXA5, and PAX6 genes have been observed in estrogen receptor (ER)-positive and HER2-negative breast cancer with axillary lymph node metastasis (ALNM), suggesting their potential as therapeutic targets." (PMID 40517231, 2025). "Furthermore, in addition to highly methylated AKR1B1, RASGRF2 and CRMP1 gene promoters, BNIP3, GSTP1, HOXA5 and PAX6 gene promoters were also methylated in ER-positive and HER2-negative breast cancer with ALNM, which may serve as candidate methylation biomarkers." (PMID 36454866, 2022). "The results showed that compared with negative lymph node breast cancer tissues, RHOF promoter methylation levels were decreased in positive lymph node breast cancer tissues, while AKR1B1, RASGRF2, and CRMP1 gene promoter methylation levels were increased." (PMID 36454866, 2022). "And compared with ER-positive and HER2-negative breast cancers without ALNM, the methylation levels of AKR1B1, RASGRF2, CRMP1, BNIP3, GSTP1, HOXA5, and PAX6 promoter were increased in ER-positive and HER2-negative breast cancers with ALNM." (PMID 36454866, 2022). "Targeted bisulfite sequencing showed that the promoter methylation levels of AKR1B1, BNIP3, CRMP1, GSTP1, HOXA5, PAX6, and RASGRF2 were increased in ER-positive and HER2-negative breast cancers with ALNM, compared with ER-positive and HER2-negative breast cancers without ALNM." (PMID 36454866, 2022).
glioma (3 papers, 2020 to 2023). A benign or malignant brain and spinal cord tumor that arises from glial cells (astrocytes, oligodendrocytes, ependymal cells). "RASGRF2 targeted by probe cg06829830 has also been predicted to be contribute to the pathogenesis of glioma at methylation level." (PMID 33329750, 2020). "Nomogram and calibration curves further confirmed that the prognostic model composed of SYT1, CREB3L3, ITPR1, RASGRF2, PDX1, and RASGRF1 has good stability and potential application value for poor prognosis in patients with glioma." (PMID 37090987, 2023). "The LASSO regression model was constructed to screen the molecular models related to glioma prognosis, which were composed of SYT1, CREB3L3, ITPR1, RASGRF2, PDX1, and RASGRF1." (PMID 37090987, 2023). "Interestingly, the imbalance of oxidative stress-related pathways was also exhibited in glioma tissues, and the expression of SYT1, CREB3L3, ITPR1, RASGRF1, RASGRF2, and PDX1 were significantly different from that of para-cancerous tissues." (PMID 37090987, 2023).
lung carcinoma (3 papers, 2017 to 2025). "They stressed that RasGRF2 expression was suppressed in lung carcinoma by aberrant methylation." (PMID 33709437, 2021). "We identified six RASGRF2 fusions in PDAC, five in prostate cancers, and three in NSCLC/lung cancers." (PMID 40615519, 2025).
lymphoma (3 papers, 2009 to 2019). A malignant (clonal) proliferation of B- lymphocytes or T- lymphocytes which involves the lymph nodes, bone marrow and/or extranodal sites. "The Vav1 and Rasgrf2 gene deficiencies seem to contribute differently to these two lymphoma stages." (PMID 20011522, 2009). "However, when combined with the inactivation of the Vav1 gene, the Rasgrf2 gene deficiency promotes a two–fold increase in the development of “widespread” lymphomas, shorter latency periods for the development of the disease, and enhanced mortality/sickness rates." (PMID 20011522, 2009). "Instead, we detected a reduction in RASGRF2 transcript levels in 81% of all the human lymphoma cases analyzed." (PMID 20011522, 2009). "We next analyzed whether the expression levels of VAV1 and RASGRF2 genes were significantly altered in specific subgroups of patients affected of leukemia, lymphoma or myeloma." (PMID 20011522, 2009). "The take home message of these studies is that the human VAV1 and RASGRF2 genes do not show a consistent and generalizable change pattern in hematopoietic tumors such as lymphomas, leukemias or myelomas." (PMID 20011522, 2009).
alcoholism (2 papers, 2016 to 2020). "A relationship between the RASGRF2 G>A polymorphism and alcoholism itself is also biologically plausible." (PMID 27992614, 2016). "RasGRF2 can activate the MAPK/ERK pathway, which is involved in neurotransmission (especially through dopamine receptors and transporters) and thus potentially associated with reward mechanisms in alcoholism." (PMID 27992614, 2016). "We found an association of the RASGRF2 G>A polymorphism (rs26907) with the presence of AC in male alcoholic patients, but not with the presence of alcoholism itself (defined as AA or AD, according to DSM-IV criteria)." (PMID 27992614, 2016). "These IMAGEN findings can be explained by the fact that Rasgrf2 interacts with activation of the MAPK/ERK pathway, which is involved in neurotransmission through dopamine receptors and transporters and thus potentially associated with dopamine-dependent reward mechanisms in alcoholism." (PMID 32601453, 2020).
gastric cancer (2 papers, 2019 to 2024). A primary or metastatic malignant neoplasm involving the stomach. "RASGRF2 showed high levels of expression in normal tissues and diverse levels in gastric cancer patients, ranging from moderate to high." (PMID 38656888, 2024).
lymph node metastasis (2 papers, 2021 to 2022). "RasGRF2 expression was found to be significantly correlated with sex, smoking, pathological stage, T factor, lymph node metastasis, pleural invasion, vascular invasion and the pathological subtype of lung adenocarcinoma." (PMID 33709437, 2021).
melanoma (2 papers, 2021 to 2025). A malignant, usually aggressive tumor composed of atypical, neoplastic melanocytes. "Additional RASGRF2 fusions were found in other solid tumor malignancies including melanoma and ovarian cancer." (PMID 40615519, 2025). "In addition to RASGRF1 fusions, analogous rearrangements involving the related RAS-GEF RASGRF2 have been reported in melanomas and melanocytic neoplasms lacking known driver alterations." (PMID 40615519, 2025).
myeloma (2 papers, 2009 to 2020). "Further experimental investigations are needed to determine whether miR-125b-5p mediate translational repression of RASGRF2 in MM and the roles of miR-125b-5p in proliferation and apoptosis of myeloma cells." (PMID 33292265, 2020).
prostate carcinoma (2 papers, 2019 to 2025). A carcinoma that arises from epithelial cells of the prostate gland. "Hypermethylation of RASGRF2 has been associated with recurrence of prostatic cancer; BCL7B is a member of the BCL7 gene family (along with the genes BCL7A and BCL7C), in humans, the decrease in BCL7A expression is associated with development of NHL and epithelial lymphoma." (PMID 30908498, 2019). "These include FARP1 (found in 2 RASGRF2 fusions from cholangiocarcinoma and PDAC) and MSH3 (found in 6 RASGRF2 fusions from colorectal, ovarian, head and neck, pancreatic, and prostate cancers)." (PMID 40615519, 2025).
schizophrenia (2 papers, 2021 to 2024). A major psychotic disorder characterized by abnormalities in the perception or expression of reality. "RasGRF2 (Ras/Rac guanine nucleotide exchange factor) is another schizophrenia susceptibility gene that expresses heavily in neurons throughout the central nervous system." (PMID 34946848, 2021). "Additionally, links between RASGRF2 and conditions such as schizophrenia and alcohol consumption patterns underscore the gene’s impact on broader neuropsychiatric conditions." (PMID 38927744, 2024).
triple-negative breast carcinoma (2 papers, 2020 to 2021). An invasive breast carcinoma which is negative for expression of estrogen receptor (ER), progesterone receptor (PR), and human epidermal growth factor receptor 2 (HER2). "Up-regulated expression of RASGRF2 is closely associated with hippocampal neuron formation in the neonate 29, contributes to the diagnosis of triple-negative breast cancer 30, and is implicated in regulating cell polarity and tumorigenesis." (PMID 34729119, 2021). "A previous study suggested that reciprocal ANXA6 and RASGRF2 expression could delineate rapidly growing from invasive triple-negative breast cancer." (PMID 34729119, 2021).
acute lymphoblastic leukemia (1 paper, 2009). Leukemia with an acute onset, characterized by the presence of lymphoblasts in the bone marrow and the peripheral blood. "In the case of RASGRF2, we found groups of patients showing downmodulation of that gene in acute lymphoblastic leukemia." (PMID 20011522, 2009).
alcohol use disorders (1 paper, 2024). "Certain haplotypes of RASGRF2 are linked to increased reward sensitivity and higher risk for alcohol use disorders." (PMID 38927744, 2024).
alcoholic liver cirrhosis (1 paper, 2016). A disorder of the liver characterized by the presence of fibrotic scar tissue instead of healthy liver tissue. "Genotypic and allelic frequencies of the KRAS and RASGRF2 polymorphisms in alcoholic patients vs. controls and in patients with alcoholic cirrhosis vs. patients without alcoholic liver disease." (PMID 27992614, 2016).
breast tumor (1 paper, 2019). "Given that activation of RasGRF2 by Ca2+ mobilizing oncogenes constitutes an important axis for Ras activation by several RTKs and GPCRs, this study provides a strong rationale to target these hard-to treat breast tumors with EGFR targeted therapies in combination with inhibition of RasGRF2." (PMID 30719209, 2019).
Cirrhosis (1 paper, 2016). A chronic disorder of the liver in which liver tissue becomes scarred and is partially replaced by regenerative nodules and fibrotic tissue resulting in loss of liver function. "The A allele of the RASGRF2 polymorphism (rs26907) was significantly more prevalent among alcoholic patients with cirrhosis (23.2%) compared to alcoholic patients without ALD (14.2%)." (PMID 27992614, 2016).
colon cancer (1 paper, 2009). "Consistent with this possibility, it has been recently demonstrated that the overexpression of RasGRF2 affects negatively the transforming properties of a colon cancer cell line." (PMID 20011522, 2009). "Moreover, it has been demonstrated that the overexpression of RasGRF2 negatively affects the transforming properties of a colon cancer cell line." (PMID 20011522, 2009).
dependence (1 paper, 2016). "Given this background, it is difficult to reconcile the previous findings showing an association of the G allele of the RASGRF2 SNP with higher alcohol intake and our own data showing an association of the A allele with ALD, particularly in patients with dependence." (PMID 27992614, 2016).
developmental delay (1 paper, 2024). "However, while our data align with existing research, definitive links between our patient’s developmental delay and the specific chromosomal translocation affecting RASGRF2 require further functional studies." (PMID 38927744, 2024). "Similarly, another patient (ID: 269277), with a duplication affecting the RASGRF2 gene, displayed overgrowth and mild global developmental delay, though the pathogenicity of this duplication remains uncertain." (PMID 38927744, 2024). "Variations in RASGRF2 have so far not been reported in developmental delay, but research on the RASGRF2 gene underscores its significance in various aspects of neurodevelopment, including synaptic plasticity, signaling pathways, and behavioral responses." (PMID 38927744, 2024).
leukemia (1 paper, 2009). A malignant (clonal) hematologic disorder, involving hematopoietic stem cells and characterized by the presence of primitive or atypical myeloid or lymphoid cells in the bone marrow and the blood. "It will be really important in the future to obtain a large group of T–cell lymphoma/leukemia samples in order to assess the specific implication of Vav1 and RasGRF2 in this tumorigenic context." (PMID 20011522, 2009).
liver disease (1 paper, 2016). "Post-hoc power calculations for our study showed a power of 16.4% for detecting differences between minor allele frequency of RASGRF2 SNP between alcoholics and controls and a power of 77.9% for differences between alcoholics with AC and those without liver disease." (PMID 27992614, 2016).
liver fibrosis (1 paper, 2016). "In light of these previous data and our own results, we could hypothesize that the presence of the A allele in the RASGRF2 polymorphism may potentiate the RasGRF2-mediated ethanol-induced inflammatory response, leading to macrophage activation and an increased risk of liver fibrosis." (PMID 27992614, 2016).
lung adenocarcinoma (1 paper, 2021). A carcinoma that arises from the lung and is characterized by the presence of malignant glandular epithelial cells. "The apparent association of RasGRF2 expression with the clinical characteristics of patients with lung adenocarcinoma is interesting." (PMID 33709437, 2021). "Both RasGRF2 and pECT2 activate Rho, thus triggering various signaling pathways associated with tumor invasion and mobility of lung adenocarcinoma." (PMID 33709437, 2021). "In the present study, however, we found that 56% (100/179) of the lung adenocarcinomas we examined showed HS with anti‐RasGRF2 antibody." (PMID 33709437, 2021). "The expression of Ras‐specific guanine nucleotide‐releasing factor 2 (RasGRF2) in lung adenocarcinomas was examined using immunohistochemistry in relation to clinicopathological characteristics and prognosis." (PMID 33709437, 2021). "In the present study, we examined that the expression of RasGRF2 in lung adenocarcinoma using immunohistochemistry." (PMID 33709437, 2021). "In this study, we examined the expression of RasGRF2 in lung adenocarcinoma." (PMID 33709437, 2021). "Multivariate analysis using the Cox proportional hazards model indicated that lymphatic permeation and vascular invasion were independent factors predictive of poor survival in patients with lung adenocarcinoma, whereas RasGRF2 expression was not." (PMID 33709437, 2021).
lymphoblastic lymphoma (1 paper, 2009). A lymphoma composed of immature small to medium-sized precursor lymphoid cells (lymphoblasts). "We have shown in this report that the double Vav1/Rasgrf2 gene deficiency favors the development and progression of lymphoblastic lymphoma–like tumors in mice." (PMID 20011522, 2009). "Cantrell’s group has also shown that the elimination in thymocytes of RhoA function, a GTPase activated by Vav family proteins, leads to a lymphoblastic lymphoma very similar to the disseminated tumors found in Vav1–/– and Vav1–/–;Rasgrf2–/– mice." (PMID 20011522, 2009). "However, our present data puts a note of caution on those possible avenues, since they indicate that the blockage of Vav family–dependent signaling could be highly counterproductive in the case of lymphoblastic lymphoma patients with reduced levels of RASGRF2 gene expression in tumor cells." (PMID 20011522, 2009).